PMVK (phosphomevalonate kinase)
Description:
Catalyzes the reversible ATP-dependent phosphorylation of mevalonate 5-phosphate to produce mevalonate diphosphate and ADP, a key step in the mevalonic acid mediated biosynthesis of isopentenyl diphosphate and other polyisoprenoid metabolites.
Synonyms: PMKase; PMK; PMKA; HUMPMKI; POROK1
Tractability: PROTAC: ubiquitination databases record sites on it; its protein half-life has been measured.
Gene: Protein-coding gene on chromosome 1 (154,924,732 to 154,937,008, reverse strand). Ensembl gene ENSG00000163344.
Subcellular location: Cytoplasm, cytosol
Pathways (Reactome):
Metabolism: Activation of gene expression by SREBF (SREBP); Lanosterol biosynthesis
Gene Ontology:
Molecular function: ATP binding; phosphomevalonate kinase activity; protein binding
Biological process: cholesterol biosynthetic process; response to cholesterol; sterol biosynthetic process; isopentenyl diphosphate biosynthetic process, mevalonate pathway; farnesyl diphosphate biosynthetic process, mevalonate pathway; geranylgeranyl diphosphate biosynthetic process; zymosterol biosynthetic process
Cellular component: cytosol; extracellular exosome; membrane; peroxisome; cytoplasm
Genetic constraint (gnomAD): Loss-of-function variants: 11 observed, 20.94 expected, observed/expected ratio (o/e) 0.53, 90% interval 0.33 to 0.87. The upper end of that interval is the gene's LOEUF score, 0.87, which puts it in group 3 of 6, group 1 being the genes least tolerant of losing a copy. Missense variants: 200 observed, 231.49 expected, observed/expected ratio (o/e) 0.86, 90% interval 0.77 to 0.97. Synonymous variants: 99 observed, 93.3 expected, observed/expected ratio (o/e) 1.06, 90% interval 0.9 to 1.25.
Homologues: Orthologues: chimpanzee PMVK (99% identical), rabbit PMVK (90% identical), pig PMVK (89% identical), dog PMVK (88% identical), rat Pmvk (85% identical), guinea pig PMVK (85% identical), macaque PMVK (83% identical), mouse Pmvk (83% identical), zebrafish pmvk (54% identical), Caenorhabditis elegans F32D8.13 (42% identical), Drosophila melanogaster Pmvk (41% identical).
Diseases named in the same sentence as PMVK in open-access papers:
PMVK is named in the same sentence as 27 diseases in open-access papers, as found by Europe PMC text mining. Sharing a sentence is not in itself a finding about the gene and the disease. The quoted sentences say what the papers report.
breast carcinoma (4 papers, 2022 to 2025). "The expression of PMVK in breast cancer tissue as reported in the TCGA database was higher than that in normal tissue adjacent to tumour tissue." (PMID 36323841, 2022). "We confirmed the relationship between miR-874 and PMVK expression and between miR-874 and SREBF2 expression in clinical specimens by analysing the TCGA breast cancer dataset." (PMID 36323841, 2022). "To validate the RNA-seq results, we assessed whether miR-874 affects endogenous PMVK and SREBF2 expression in breast cancer cell lines." (PMID 36323841, 2022).
porokeratosis (4 papers, 2015 to 2024). A clonal proliferation of abnormal keratinocytes characterized by the development of localized or multiple atrophic skin patches surrounded by an annular keratotic ring called cornoid lamella. "Mutations in some of the newly identified genes were instead linked to porokeratosis affecting specific areas of the body; for example, PMVK and MVD mutations are linked to porokeratosis localized to the genitals and around the eyes, respectively." (PMID 26202976, 2015). "Our findings suggest that the accumulation of abnormal metabolites or the shortage of cholesterol/isoprenoids may cause PMVK deficiency-associated porokeratosis." (PMID 27052676, 2016). "Our findings suggest that PMVK is a potential novel gene involved in the pathogenesis of DSP and PMVK deficiency or abnormal keratinocyte apoptosis could lead to porokeratosis." (PMID 27052676, 2016). "This search identified mutations in three additional genes (called PMVK, MVD and FDPS) that are all linked to porokeratosis." (PMID 26202976, 2015). "Notably, the PM subtype of porokeratosis shows particular alterations in the MVK and PMVK genes, resulting in decreased expression of the respective enzymes." (PMID 39219867, 2024).
liver cancer (2 papers, 2023 to 2024). An epithelial or non-epithelial malignant neoplasm that arises from the liver. "High PMVK expression is associated with shorter survival in liver cancer patients." (PMID 37958351, 2023). "TCGA database analysis showed that PMVK expression was negatively correlated with CD8+ T cells in liver cancer tissues." (PMID 39325640, 2024). "In the case of liver cancer, it has been shown that the PMVK protein level is higher in tumors than in non-tumor areas." (PMID 37958351, 2023).
lung carcinoma (2 papers, 2022 to 2025). "In agreement, PMVK loss also leads to enhanced radiosensitivity in lung cancer cells and apoptosis in various cancer cells." (PMID 40597205, 2025). "Our findings indicate that the MVK, GGPS1 and PMVK expression was correlated with HMGA1 gene expression in lung cancer tissues, but not in normal lung tissue." (PMID 35805937, 2022).
prostate carcinoma (2 papers, 2013 to 2020). A carcinoma that arises from epithelial cells of the prostate gland. "Genes involved in steroid synthesis included CYP21A2, HSD17B2, ITGA6, IDI2, MAP2K1, PMVK, TSPO, and may correspond to androgen dependent growth of prostate cancer." (PMID 32226005, 2020).
anxiety disorder (1 paper, 2021). A category of psychiatric disorders which are characterized by anxious feelings or fear often accompanied by physical symptoms associated with anxiety. "The stop-strengthening variant in PMVK was associated with increased risk of Type 1 diabetes while the stop-strengthening variant in VPS53 was associated with a protective effect against anxiety disorders." (PMID 33750777, 2021).
Arrhythmia (1 paper, 2024). Any cardiac rhythm other than the normal sinus rhythm. "Eight of these associations were novel (LMNA, SMAD6, HSPB9, TMEM95, KLF1, TET2, NME3, KDM5B) and 5 genes have previously been linked to arrhythmias (SCN5A, TTN, RPL3L, PKP2, PMVK)." (PMID 38390584, 2024).
Arthritis (1 paper, 2023). Inflammation of a joint. "PMVK deficiency expands the genetic spectrum of systemic autoinflammatory diseases, characterized by recurrent fevers, arthritis, and cytopenia and thus should be included in the differential diagnosis and genetic testing for systemic autoinflammatory diseases." (PMID 37364720, 2023).
atrial fibrillation (1 paper, 2024). A disorder characterized by an electrocardiographic finding of a supraventricular arrhythmia characterized by the replacement of consistent P waves by rapid oscillations or fibrillatory waves that vary in size, shape and timing and are accompanied by an irregular ventricular response. "Atrial fibrillation (ICD10 code I48) was associated with rare variation in 8 genes (TTN, RPL3L, KLF1, TET2, NME3, KDM5B, PKP2, PMVK)." (PMID 38390584, 2024). "Atrial fibrillation was associated with rare variations in 8 genes (TTN, RPL3L, KLF1, TET2, NME3, KDM5B, PKP2, PMVK)." (PMID 38390584, 2024). "Four of these genes have previously been linked in GWAS to atrial fibrillation (TTN, RPL3L, PKP2, PMVK)." (PMID 38390584, 2024).
bipolar disorder (1 paper, 2021). A disorder of the brain that causes unusual shifts in mood, energy, activity levels and the ability to carry out day-to-day tasks. "SLC8A3 and PMVK have been associated with bipolar disorder and Parkinson disease, respectively." (PMID 33314580, 2021).
brain tumor (1 paper, 2023). "Additionally, the observation of downregulation of phosphomevalonate kinase is significant as the brain tumor initiating cells (BTIC) are maintained by the metabolism occurring via the mevalonate pathway." (PMID 37174677, 2023).
diabetes (1 paper, 2021). "The associations between PMVK and diabetes, and SHMT2 and diseases of the salivary gland, were replicated in the UKB and PMBB respectively (PMVKP = 0.00727, SHMT2P = 0.005515)." (PMID 33750777, 2021). "Finally, the novel association between stop-strengthening and pLOF variants in PMVK with diabetes further strengthens existing genetic and epidemiological evidence linking the mevalonate pathway to diabetes." (PMID 33750777, 2021). "Our data is the first to establish a putative link between PMVK and diabetes." (PMID 33750777, 2021).
glioblastoma (1 paper, 2023). The most malignant astrocytic tumor (WHO grade IV). "Therefore, we envision that a reduction in phosphomevalonate kinase in the present study with CA could have an inhibitory effect on the maintenance of BTIC in glioblastomas, thus possibly preventing recurrence of this devastating cancer and providing a beneficial therapeutic effect." (PMID 37174677, 2023).
hepatocellular carcinoma (1 paper, 2024). A malignant tumor that arises from hepatocytes. "Here, it is shown how phosphomevalonate kinase (PMVK) allows hepatocellular carcinoma (HCC) cells to overcome the anti‐tumor immunity mediated by CD8+ T cells." (PMID 39325640, 2024). "In contrast, there was no change in the pAKT1 of CD8+ T cells cultured with concentrated PMVK knockout hepatoma cell medium." (PMID 39325640, 2024).
lung adenocarcinoma (1 paper, 2022). A carcinoma that arises from the lung and is characterized by the presence of malignant glandular epithelial cells. "Expression levels of the GGPS1 and PMVK genes were only significantly correlated with HMGA1 expression in lung adenocarcinoma." (PMID 35805937, 2022).
ovarian carcinoma (1 paper, 2020). A malignant neoplasm originating from the surface ovarian epithelium. "Upon validation with complementary IHC staining for FFPE HGSOC tissue specimens, we identified six protein biomarkers to predict the prognosis of HGSOC; expression levels of AAT, NFKB, PMVK, VAP1, FABP4, and PF4 in ovarian cancer tissue were associated with PFS." (PMID 32224886, 2020).
preeclampsia (1 paper, 2025). Preeclampsia is a hypertensive disorder of pregnancy that is characterized by new-onset hypertension with proteinuria presenting after 20 weeks of gestation, and depending on mild or severe forms may initially present with severe headache, visual disturbances, and hyperreflexia. "The mevalonate pathway gene PMVK also emerged, with higher genetically predicted expression (linked to higher methylation at cg16318349) associated with lower odds of preeclampsia." (PMID 41220585, 2025). "The results revealed that the expressions of ATG16L1, NSUN2 and PMVK were significantly downregulated in placental tissues from preeclampsia patients, whereas other key genes such as CDC25A and MAP3K14 did not vary significantly between groups." (PMID 41220585, 2025). "Ultimately, functional studies in relevant cell and animal models are essential to confirm the causal impact of ATG16L1, PMVK, MAP3K14, NSUN2, and CDC25A on senescence phenotypes and preeclampsia pathogenesis." (PMID 41220585, 2025). "After outliers removal, the expressions of ATG16L1, PMVK and NSUN2 were found to be associated with odds of preeclampsia via the IVW method." (PMID 41220585, 2025). "Our findings implicate several genes operating through diverse pathways—including ATG16L1, MAP3K14, PMVK, CDC25A, and NSUN2—as potential mediators linking senescence processes to odds of preeclampsia." (PMID 41220585, 2025). "Key genes (ATG16L1, PMVK, MAP3K14, NSUN2, CDC25A) link cellular senescence to preeclampsia, offering insights for mechanistic studies and therapeutic targeting." (PMID 41220585, 2025). "Placental RT-PCR showed upregulated ATG16L1 and downregulated PMVK, MAP3K14, NSUN2, and CDC25A in preeclampsia." (PMID 41220585, 2025). "In conclusion, this multi-omics MR study, combined with preliminary experimental insights, pinpoints ATG16L1, PMVK, MAP3K14, NSUN2, and CDC25A as key candidate genes potentially mediating the link between cellular senescence pathways and odds of preeclampsia." (PMID 41220585, 2025). "These preliminary experimental findings lend support to the potential relevance of ATG16L1, PMVK, MAP3K14, NSUN2, and CDC25A dysregulation in preeclampsia pathophysiology." (PMID 41220585, 2025). "Synthesizing these results, dysregulation across interconnected pathways—autophagy (ATG16L1), inflammation (MAP3K14), metabolism (PMVK), cell cycle (CDC25A), and RNA methylation (NSUN2)—appears to converge on promoting placental cellular senescence, contributing to preeclampsia pathophysiology." (PMID 41220585, 2025).
psoriasis (1 paper, 2023). An autoimmune condition characterized by red, well-delineated plaques with silvery scales that are usually on the extensor surfaces and scalp. "Although these three enzymes are proven to affect the function of KCs and psoriasis-related cytokines, there has been no research on the involvement of MVK, PMVK, and MVD in psoriasis." (PMID 37234169, 2023).
tumor (11 papers, 2019 to 2025). "The inhibitory effect of PMVK loss on tumor growth in immunocompetent C57BL/6J mice was more obvious than that in immunodeficient BalB/c nude mice." (PMID 39325640, 2024). "Adeno‐associated virus 8 (AAV8) restoration of PMVK expression promoted tumor growth and increased serum levels of TC and TG in CKO mice." (PMID 36808719, 2023). "PMVK regulates 4‐Ac‐GABA levels in tumor cells while also inhibiting the infiltration and activation of TME‐associated CD8+ T cells." (PMID 39325640, 2024). "We have shown that combined therapies that simultaneously target PMVK and PD‐1 can significantly inhibit tumor growth and are significantly more efficacious than individual therapies." (PMID 39325640, 2024). "The MREs ACAT1, ACAT2, FDFT1, FDPS, HMGCL and PMVK were highly expressed in basal tumor cells and urothelial cells." (PMID 39521858, 2024). "As a result, we have found that PMVK plays key roles in embryonic development and tumor growth, while PMVK‐mediated β‐catenin p‐Ser184 phosphorylation is also significantly upregulated in both key nodes." (PMID 36808719, 2023). "To further investigate the effects of PMVK and β‐catenin Ser184 phosphorylation on tumor growth, we delivered PMVK or β‐catenin (WT and S184A/D) via AAV8 in WT mice." (PMID 36808719, 2023). "CD8+ T cell depletion can partially restore tumor growth inhibition induced by knockdown PMVK." (PMID 39325640, 2024). "Further analysis showed that PMVK was mainly enriched in tumor cells of HCC tissues." (PMID 39325640, 2024). "Thus, PMVK appears to stabilize the β‐catenin protein, which is in turn necessary to maintain cell proliferation and tumor growth." (PMID 36808719, 2023). "ECI2, PPT2, ACSM3, PMVK, and IDO1 were low expressed in the prognosis of high-risk patients, which may be tumor suppressor factors." (PMID 37256178, 2023). "In tumor samples from 10 HCC patients, PMVK, GAD1, and ACAT1 were significantly upregulated relative to matched normal liver tissues." (PMID 39325640, 2024). "In HCCs, depletion of PMVK is required to facilitate CD8+ T cell activation and their subsequent suppression of tumor growth." (PMID 39325640, 2024). "Both PMVK and SREBF2 expression were elevated in tumour tissues (n = 1093) compared with adjacent normal tissues (n = 104), whereas miR-874 expression was decreased in tumour tissues compared with corresponding normal tissues." (PMID 36323841, 2022). "A Random Forest Classifier model showed that, in eight of the nine tumor cohorts, these patterns were largely determined by a small subset of transcripts, comprised of DHCR24, HMGCS2, PMVK and ACAT1/2." (PMID 31242205, 2019). "Collectively, these data suggest that liver‐specific PMVK deletion significantly slows HCC development by reducing cell proliferation and cholesterol and triglyceride levels whereas PMVK‐mediated phosphorylation of β‐catenin Ser184 strongly promotes tumor growth." (PMID 36808719, 2023). "In addition, deletion of PMVK in mouse liver did not change the level of GABA in tumor tissues." (PMID 39325640, 2024).
cancer (8 papers, 2019 to 2025). A tumor composed of atypical neoplastic, often pleomorphic cells that invade other tissues. "Although the mevalonate pathway has been implicated in various aspects of cancer development and progression, the role(s) of PMVK remains unknown." (PMID 36808719, 2023). "Little is known about the function of the other H2Bub1-dependent peroxisome-related genes PEX6 and PMVK in cancers." (PMID 40597205, 2025). "PMVK thus represents a novel therapeutic target in cancers that rely on aberrant β‐catenin signaling." (PMID 36808719, 2023). "Thus, to circumvent the problem, impacting pathways controlled by Myc such as the mevalonate pathway by decrease in phosphomevalonate kinase could be considered as one of the strategies to inhibit its role in cancer-cell proliferation." (PMID 37174677, 2023). "Furthermore, the decrease in phosphomevalonate kinase could be harnessed for alerting the immune system to the pathways that guard the cancers from being attacked because the mevalonate pathway is pivotal to cancer immune surveillance." (PMID 37174677, 2023).
infection (1 paper, 2023). The state of being infected such as from the introduction of a foreign agent such as serum, vaccine, antigenic substance or organism. "By 5 days post-infection with ZikV, the fold change in gene expression for all genes involved in the MVA pathway was significantly increased in W− cells but not in W+ cells, except for phosphomevalonate kinase (AALF024095)." (PMID 37811984, 2023).
PMVK also shares sentences with these, for which no sentence is quoted: diseases of the salivary gland (1 paper); keratinization disorders (1); metastatic tumors (1); Parkinson disease (1); serous ovarian carcinoma (1); Type 1 diabetes (1).